NFATC2 (nuclear factor of activated T cells 2)
Diseases named in the same sentence as NFATC2 in open-access papers (continued):
Sharing a sentence is not in itself a finding about the gene and the disease.
cancer (continued). "For instance, MAP3K8, MAP3K13, NCF2, NF-κB (family), NFATC2, NF-κB (complex), and NR2F2 were significantly disturbed by myricetin treatment, which are belonging to cancer related MAPK/NF-κB inflammatory signaling pathway." (PMID 30956980, 2019). "Specific missense mutation matches have been found to six proteins from the COSMIC Cancer Gene Census database (FLNA, RPL22, SDHA, NFATC2, NPM1, and CLTCL1)." (PMID 31316139, 2019). "Overall, the data indicated NFATc2 induces TIC, cancer initiating phenotypes and drug resistance through upregulating SOX2 expression." (PMID 28737489, 2017). "Similar to NFATc2, SOX2 was also upregulated in A549 induced for cisplatin resistance (A549 CR) but on NFATc2 knockdown, SOX2 levels were repressed, suggesting NFATc2/SOX2 coupling was functionally active in resistant cancer cells." (PMID 28737489, 2017). "Using multiple analyses of cancer cells and tumorspheres, we observed SOX2 was the most consistently altered factor with the highest magnitude of change when NFATc2 expression or calcineurin activity were manipulated." (PMID 28737489, 2017). "Using log rank test and Kaplan-Meier survival analysis, we showed tumors with high level NFATc2 expression had significantly shorter recurrence-free survival (RFS) and cancer-specific overall survival (OS)." (PMID 28737489, 2017). "Therefore, the differentially methylated specific genes (NTRK2, MAPKAPK2, CRK, and NFATC2) and the dysregulated miRNAs (mir-148a, mir-374a and mir-494) in the MAPK and ErbB pathways cause cell proliferation, adhesions and migration and the immune cell infiltration to cancer cells during early HCC." (PMID 27821810, 2016). "Research indicates that NFATC2 regulates the expression of matrix metalloproteinase 13 (MMP13) in BC cells through interactions with other proteins, thereby promoting the invasiveness of cancer cells, which provides a new therapeutic target for BC treatment." (PMID 40496857, 2025). "However, deepC-SV could not find any SE involved with three cancer-related genes (17.6%, 3/17): NFATC2 and SALL4 in MCF7, TERT in HCC1954." (PMID 39322849, 2024). "This study employed a candidate-based approach and the involvement of other potential NFATc2 and SOX2 targets in cancer phenotypes is not addressed." (PMID 28737489, 2017).
infection (21 papers, 2011 to 2025). The state of being infected such as from the introduction of a foreign agent such as serum, vaccine, antigenic substance or organism. "SARS-CoV-2 infection triggered NFATC2 translocation into the nuclei of endothelial and other cells by day 1, persisting through day 3 post-infection." (PMID 41253746, 2025). "We show selective impacts of NFATc1 and/or NFATc2 genetic ablations on the long-term inflation of MCMV-specific CD8+ T cell responses despite largely maintained responses to acute infection." (PMID 38346075, 2024). "The expression of NFATc2 and c3 in the liver of M. fortis were significantly increased at day 13 post-infection, at which time the amount of cell adherence was the greatest." (PMID 37794085, 2023). "Instead, our results point to differences in the expression and activation of NFATc1 and NFATc2 as a primary mechanism driving enhanced lytic infection in T2 EBV-infected B cells." (PMID 32059024, 2020). "We and others showed that during the early phase of cellular infection by T. cruzi, the expression profiles of AP-1 transcription factor network genes including NFATC2, FOS and TGF-β are dysregulated by the parasite." (PMID 33322418, 2020). "NFATc2 translocation in response to SC was apparent as early as 30 min after infection and sustained over a 2-h period (Fig5A and B)." (PMID 25637383, 2015). "Wholesale, longer-term inactivation of NFATC2, which also plays important roles in T cells, might compromise important aspects of a productive adaptive immune response during mycobacterial infection, and our adult infection studies were over relatively short time frames (2–3.5 weeks)." (PMID 36516756, 2022). "Instead, we find that T2 LCLs express much higher levels of activated NFATc1 and NFATc2, and that cyclosporine (an NFAT inhibitor) and knockdown of NFATc2 attenuate constitutive lytic infection in T2 LCLs." (PMID 32059024, 2020). "ZEB1 and AP1 have been shown to be involved in HIV latency and NFATC2 is essential for productive infection of non-activated T-cells." (PMID 35513551, 2022). "Thus, we propose that increased IRF4 expression in T1 LCLs reduces lytic infection not only by attenuating BCR signaling, including NFAT activation, but also by decreasing NFATc1 and NFATc2 expression." (PMID 35472072, 2022). "To further address whether NFATc2 is a positive regulator of lytic infection in the context of T2 EBV-transformed LCLs, we knocked down NFATc2 in lytic type 2 LCLs using either a CRISPR/Cas9 approach or an NFATc2 specific shRNA." (PMID 32059024, 2020). "In the brains of PD-L1−/− mice a number of upstream regulators were enriched during acute infection but reduced or below threshold during persistent infection (e.g., IFN-γ, IL-15, NOS, NFATC2, and IL12-A), suggesting dynamic epigenetic changes in these genes in the absence of PD-1 signaling." (PMID 31105690, 2019). "Furthermore, using immunofluorescence ED1+/ED2+ TM isolated from PBS injected testes showed a cytoplasmic localization of NFATC2, whereas NFATC2 is found in the nucleus in TM obtained from UPEC infected inflamed testis seven days post infection." (PMID 22164293, 2011). "For instance, HAVCR2 involved in NFAT dephosphorylation was not significantly regulated in MA08 infection and was accompanied by upregulation of IL2 and downregulation of NFATC2 (nuclear factor of activated T cells, cytoplasmic 2)." (PMID 34671358, 2021).
cardiovascular disease (3 papers, 2019 to 2025). "Other upstream regulators were associated with cardiovascular disease, including hypertrophy (Nfatc2) and oxidative stress responses (Nfe212)." (PMID 31789590, 2019). "NFAT protein family is the main substrate of CaN and includes NFAT1 (NFATc2), NFAT2 (NFATc1), NFAT3 (NFATc4), NFAT4 (NFATc3) and NFAT5, among which NFATc3 protein is highly related to the development of cardiovascular disease." (PMID 37735624, 2023).
infectious disease (1 paper, 2023). A disorder directly resulting from the presence and activity of a microbial, viral, or parasitic agent in humans. "Recently, we showed in infectious disease research that T. cruzi dysregulates the expression profile of host piRNAs computationally predicted to target profibrotic molecules including TGFB1, FOS, and NFATC2 in primary human cardiac myocytes." (PMID 36936778, 2023).
retinopathies (1 paper, 2015). "Together, these studies show a clear role for NFAT-signaling in TNFα-induced retinal leukostasis, and identify NFATc2 and NFATc4 as potentially valuable therapeutic targets for treating retinopathies in which TNFα plays a pathogenic role." (PMID 26527057, 2015).
NFATC2 also shares sentences with these, for which no sentence is quoted: Ewing sarcoma (13 papers); hepatocellular carcinoma (9); AIDS (8); bone cyst (6); prostate carcinoma (5); liver cancer (4); B cell lymphoma (3); bone cancer (3); mesenchymal chondrosarcoma (3); myoepithelioma (3); neurodegenerative disease (3); non-small cell lung carcinoma (3); ovarian carcinoma (3); renal carcinoma (3); triple-negative breast carcinoma (3); aneurysmal bone cyst (2); bladder cancer (2); cervical cancer (2); chronic kidney disease (2); cognitive decline (2); esophageal cancer (2); hemangioma (2); leukemia (2); lung squamous cell carcinoma (2); lymph node metastasis (2); pulmonary arterial hypertension (2); Type 2 Diabetes (2); ulcerative colitis (2); arteriovenous malformation (1); Arthritis (1).
A further 70 diseases each share a sentence with NFATC2 in 1 paper.